CYP7A1 (cytochrome P450 family 7 subfamily A member 1)
Diseases named in the same sentence as CYP7A1 in open-access papers (continued):
Sharing a sentence is not in itself a finding about the gene and the disease.
cancer (7 papers, 2018 to 2024). A tumor composed of atypical neoplastic, often pleomorphic cells that invade other tissues. "CYP7A1+ hepatocytes upregulated genes associated with stress response, inflammation and cancer‐associated pathways and downregulated the normal hepatocyte signature." (PMID 37994257, 2024). "Further understanding of the mechanisms that suppress Cyp7a1 would also be useful for cancer treatments that aim to block FGFR468." (PMID 34362888, 2021). "Here, we study the novel non-tumorigenic analogue FGF19-M52 as putative drug to inhibit Cyp7a1, reduce BA synthesis and eventually protect against BA-induced cancer in the liver." (PMID 30464200, 2018). "The expression of LPCAT1, NDRG1, G6PD, CYP7A1, SPP1, SFN, and CDCA8 was significantly higher in cancer tissues than in paraneoplastic tissues, whereas the expression of DNASE1L3 was significantly lower in cancer tissues." (PMID 37717019, 2023). "These qPCR results confirmed a similar distribution of gene expression; overexpression of CYP1B1, CYP7A1, CYP17A1, and CYP19A1, and repression of CYP1A2, CYP2B6, CYP2C19, and CYP26A1 was observed in cancer tissues." (PMID 31258835, 2019). "CYP450 plays crucial roles in these intertwined mechanisms of cholesterol homeostasis, such as CYP7A1, 27A1, 46A1, CYP8B1, and CYP39A1, which are cholesterol oxidation products whose expression may be dysregulated in inflammation-related diseases, including cancer." (PMID 35003516, 2021). "However, since some tumors have relatively normal gene expression level and there is interindividual variability in samples, the differences in CYP1B1 and CYP7A1 expression levels between normal and cancer tissues were not considered statistically significative." (PMID 31258835, 2019).
cardiovascular diseases (3 papers, 2022 to 2025). "The association of these CYP7A1 polymorphisms with cardiovascular diseases has been mostly explained by increased LDL-C levels." (PMID 39207177, 2025). "Taken together, our results and the different distribution of CYP7A1 polymorphisms based on ethnicity, suggest that the effect of these SNPs on SA and other cardiovascular diseases merits further exploration in a multicentric study involving patients of diverse origins." (PMID 39207177, 2025). "Nonetheless, data from genome-wide association studies showed that both polymorphisms located downstream of the CYP7A1 enhancer region could impact LDL–C and total cholesterol plasma levels and that they were potentially associated with cardiovascular diseases." (PMID 38540230, 2024).
inflammation (2 papers, 2018 to 2021). Aberrant reaction of the microcirculation characterized by movement of fluid and leukocytes from the blood into extravascular tissues. "Our results were in line with recent studies showing a role for murine Cyp7a1 in liver inflammation in non-cancer disease models, indicative of a generalizable role for cyp7a1-mediated cholesterol–BA metabolism in diseases." (PMID 29592890, 2018).
liver (2 papers, 2024 to 2025). "The results showed that IOP‐A could significantly reduce liver and spleen indexes, limit the fatty degeneration of the liver, lower TC, TG, LDL‐C, AST, and ALT levels, increase HDL‐C levels, and up‐regulate CYP7A1 and SR‐B1 protein expression in the liver of hyperlipidemic rats." (PMID 38628208, 2024).
CYP7A1 also shares sentences with these, for which no sentence is quoted: colorectal adenoma (2 papers); Aagenaes syndrome (1); acne (1); acute coronary syndrome (1); Alagille syndrome (1); arteriosclerosis (1); bladder (1); dengue (1); Dubin-Johnson syndrome (1); dyslipidaemia (1); endothelial dysfunction (1); endotoxemia (1); fibrosis (1); growth (1); Hyperinsulinemia (1); Hypertension (1); hypothyroidism (1); inflammatory bowel disease (1); injury (1); insulin dependent diabetes mellitus (1); intestinal cancer (1); kidney failure (1); obstructive jaundice (1); osteoporosis (1); panic attacks (1); peripheral vascular disease (1); premature ovarian failure (1); primary sclerosing cholangitis (1); psoriasis (1); viral hepatitis (1).
A further 1 disease shares a sentence with CYP7A1 in 1 paper.